CYP8B1 (cytochrome P450 family 8 subfamily B member 1)
Description:
Sterol 12-alpha-hydroxylase involved in primary bile acid biosynthesis by catalyzing the 12alpha-hydroxylation of key intermediates including 7alpha-hydroxycholest-4-en-3-one, 3alpha,7alpha-dihydroxy-5beta-cholestan-26-oate and chenodeoxycholate along the classic pathway. May also hydroxylate 5beta-cholestane-3alpha,7alpha-diol (By similarity). Functions as a monooxygenase, inserting one atom of molecular oxygen into substrates while reducing the second to water, using electrons supplied by NADPH via cytochrome P450 reductase (CPR) (By similarity). Controls biliary balance of cholic acid and chenodeoxycholic acid, thereby regulating intestinal absorption of dietary lipids (By similarity).
Synonyms: CYP12; CP8B; CYPVIIIB1
Tractability: Small molecule: a structure with a bound ligand is known; a high-quality ligand is known. Antibody: UniProt predicts a signal peptide or a membrane-spanning region. PROTAC: its protein half-life has been measured; a small molecule that binds it is known.
Target class: Enzyme; Oxidoreductase
Gene: Protein-coding gene on chromosome 3 (42,856,005 to 42,875,898, reverse strand). Ensembl gene ENSG00000180432.
Subcellular location: Endoplasmic reticulum membrane; Microsome membrane
Pathways (Reactome):
Metabolism: Eicosanoids; Sterols are 12-hydroxylated by CYP8B1; Synthesis of Prostaglandins (PG) and Thromboxanes (TX); Synthesis of bile acids and bile salts via 24-hydroxycholesterol; Synthesis of bile acids and bile salts via 27-hydroxycholesterol; Synthesis of bile acids and bile salts via 7alpha-hydroxycholesterol
Gene Ontology:
Molecular function: sterol 12-alpha-hydroxylase activity; oxygen binding; heme binding; iron ion binding; monooxygenase activity; oxidoreductase activity, acting on paired donors, with incorporation or reduction of molecular oxygen
Biological process: bile acid biosynthetic process; positive regulation of intestinal cholesterol absorption; sterol metabolic process; lipid metabolic process; monocarboxylic acid biosynthetic process; response to cholesterol; response to nutrient levels
Cellular component: endoplasmic reticulum membrane
Genetic constraint (gnomAD): Loss-of-function variants: 2 observed, 2.12 expected, observed/expected ratio (o/e) 0.94, 90% interval 0.35 to 1.87. That is too few expected variants to judge how well the gene tolerates losing a copy. Missense variants: 594 observed, 633.99 expected, observed/expected ratio (o/e) 0.94, 90% interval 0.88 to 1. Synonymous variants: 221 observed, 245.58 expected, observed/expected ratio (o/e) 0.9, 90% interval 0.81 to 1.01.
Homologues: Orthologues: macaque CYP8B1 (96% identical), chimpanzee CYP8B1 (90% identical), pig CYP8B1 (81% identical), dog CYP8B1 (81% identical), mouse Cyp8b1 (75% identical), rat Cyp8b1 (74% identical), tropical clawed frog cyp8b1 (56% identical), zebrafish cyp8b1.1 (52% identical), zebrafish cyp8b1.2 (51% identical), zebrafish cyp8b1.3 (51% identical), tropical clawed frog cyp8b1.2 (48% identical). Paralogues in human: PTGIS (41% identical).
Diseases named in the same sentence as CYP8B1 in open-access papers:
CYP8B1 is named in the same sentence as 38 diseases in open-access papers, as found by Europe PMC text mining. Sharing a sentence is not in itself a finding about the gene and the disease. The quoted sentences say what the papers report.
Insulin resistance (12 papers, 2016 to 2025). Increased resistance towards insulin, that is, diminished effectiveness of insulin in reducing blood glucose levels. "12α-Hydroxylated BAs correlate with insulin resistance in humans, and 12α-hydroxylated BAs were decreased in the CYP8B1 mutation carriers." (PMID 36107630, 2022). "Other studies have found that the CYP8B1-derived 12-OH BA increase is associated with human insulin resistance and metabolic disorders such as T2DM." (PMID 36151544, 2022). "Cytochrome P450 family 8 subfamily B member 1 (CYP8B1) generates 12α-hydroxylated bile acids (BAs) that are associated with insulin resistance in humans." (PMID 36107630, 2022). "It has also been found that increased CYP8B1-derived 12-OH BAs were associated with metabolic disorders such as insulin resistance and T2DM in humans." (PMID 33252713, 2021). "Moreover, reduced CYP8B1 activity in patients with CYP8B1 loss-of-function mutations was associated with decreased insulin resistance, which is a risk factor for NAFLD." (PMID 38137523, 2023). "In healthy individuals, insulin resistance is associated with increased plasma 12α-hydroxylated BAs, suggesting that increased CYP8B1 activity may associate with insulin resistance." (PMID 36107630, 2022). "In patients with NAFLD, insulin resistance increases the activity of 12α-hydroxylase CYP8B1 expression, leading to increased BA synthesis." (PMID 40104566, 2025). "In the setting of insulin resistance, this results in more active FoxO1, followed by higher Cyp8b1 expression which in turn leads to increased CA synthesis." (PMID 34957857, 2022). "Cyp8b1−/− mice were found to be resistant to western diet-induced obesity, hepatic steatosis and insulin resistance due to reduction of lipid absorption." (PMID 33252713, 2021). "In both nondiabetic and diabetic individuals, a higher 12α-hydroxylated/non–12α-hydroxylated BA ratio correlated with greater insulin resistance, again suggesting that increased CYP8B1 activity may contribute to insulin resistance." (PMID 36107630, 2022). "This may in part explain why HFD induces glucose intolerance and insulin resistance in mice as well as why Cyp8b1-/- mice are better protected." (PMID 26824238, 2016). "In summary, these findings reveal that Cyp8b1-/- mice with a BA pool abundant in MCAs are protected against the development of several stigmata of the metabolic syndrome such as body and liver weight gain, steatosis, hypercholesterolemia and insulin resistance." (PMID 26824238, 2016). "Correspondingly, the DB group in the present study exhibited higher insulin resistance and expressed lower levels of CYP7A1 and CYP8B1, while XB supplementation significantly upregulated these enzymes." (PMID 27929393, 2016).
Obesity (8 papers, 2016 to 2025). Accumulation of substantial excess body fat. "Enrichment of A. muciniphila leads to generate more indole‐3‐lactic acid (ILA) to upregulate the expression of 12α‐hydroxylase (CYP8B1) via fat mass and obesity‐associated protein (FTO)/ N6‐methyladenosine (m6A)/YTHDF2 manner, thereby facilitating cholesterol converts to cholic acid (CA)." (PMID 39888270, 2025). "Enrichment of A. muciniphila leads to generate more ILA to facilitate cholesterol converts to CA in FTO/m6A/CYP8B1 coordinated manner, thereby reversing obesity‐related phenotypes via activating FXR in adipose tissue." (PMID 39888270, 2025). "In conclusion, we show that quercetin‐driven A. muciniphila modulates host BA metabolism in ILA/FTO/m6A/CYP8B1/CA coordinated manner to ameliorate diet‐induced obesity." (PMID 39888270, 2025). "Our study showed that UDCA administration in mice enhanced CYP7B1 expression but reduced CYP8B1 expression, leading to an elevated non-12-OH/12-OH BA ratio and a decrease in diet-induced obesity." (PMID 33252713, 2021). "Here we show that Cyp8b1−/- mice are protected against diet-induced obesity, have increased energy expenditure and increased faecal energy output." (PMID 33016185, 2020). "Cyp8b1−/- mice were found to be protected against high-fat diet induced obesity." (PMID 33016185, 2020). "CYP8B1 was one of the key enzymes of bile acids synthesis, and ablating CYP8B1 in mice led to reduced absorption of dietary triglyceride with intact triglyceride hydrolysis and improved insulin sensitivity, suggesting CYP8B1 as a potential therapeutic target for obesity and diabetes." (PMID 33980183, 2021). "Therefore, with the increased 7α-OHCnone hepatic levels, increased CYP8B1 expression and decreased levels of bile acids in both liver and gallbladder, a remaining possibility could be a decreased reabsorption of bile acids in diet-induced obesity in mice." (PMID 26795945, 2016). "Therefore, we propose that the very low production of these 12α-hydroxylated BAs in female Cyp2c70−/− mice, because of the sex-dependent Cyp8b1 suppression, reduces fat and cholesterol absorption efficiency and thereby prevents development of WTD-induced obesity and NAFLD." (PMID 34626589, 2021).
Hepatic steatosis (7 papers, 2018 to 2025). Steatosis is a term used to denote lipid accumulation within hepatocytes. "Additionally, Cyp8b1 depletion prevented the progression of hepatic steatosis and caused its regression, suggesting that inhibiting CYP8B1 may reduce susceptibility to atherosclerosis as well as hepatic steatosis." (PMID 36107630, 2022). "It has been reported that reducing the ratio of 12-OH/non-12-OH BAs by knockout of CYP8B1 could lead to the decrease in weight gain and improvement of glucose tolerance and hepatic steatosis in western diet-fed mice." (PMID 39425211, 2024). "Research indicates that knocking out CYP8B1 in mouse models of NAFLD improves hepatic steatosis." (PMID 38137523, 2023). "Concerning the regulation of BA metabolism, Cyp8b1-/- in mice specifically reduced the 12αOH BAs, which protected HFD-induced hepatic steatosis due to damaged fat absorption." (PMID 34639207, 2021). "Another study reported that LBP upregulates key enzymes, such as CYP7A1 and CYP8B1, activates FXR and SHP, and downregulates the FGFR4–β-Klotho complex, thereby reducing its inhibitory effect on CYP7A1 and enhancing bile acid synthesis in mouse models of hepatic steatosis and hypertriglyceridemia." (PMID 41480362, 2025).
Hypercholesterolemia (7 papers, 2016 to 2024). An increased concentration of cholesterol in the blood. "Cyp8b1-/- mice also display strong resistance against weight gain, hepatomegaly, steatosis, and hypercholesterolemia." (PMID 26824238, 2016). "Knockout of cholesterol 12α-hydroxylase (Cyp8b1) gene, one of the key enzymes in bile acid synthesis, could alter bile acid profile by lowering cholic acid production can inhibit intestinal cholesterol absorption and prevent hypercholesterolemia and gallstone formation." (PMID 37370162, 2023). "Taurine ameliorated hypercholesterolemia in rats fed a high cholesterol diet by directly enhancing the hepatic expression of BHMT and OATP2, which modulated the SHP and induced CYP7A1 and CYP8B1, thereby promoting cholesterol catabolism and lowering blood cholesterol levels." (PMID 39199235, 2024).
atherosclerosis (6 papers, 2014 to 2025). A disease characterized by the build-up of fatty material and calcium deposition in the arterial wall resulting in partial or complete occlusion of the arterial lumen. "In addition, inhibition of cholic acid synthesis by CYP8B1 deficiency inhibits dyslipidemia and atherosclerosis in ApoE−/− mice by decreasing intestinal lipid absorption, suggesting that cholic acid deficiency is caused by the lipid-lowering and anti-atherogenic effects of INT-767." (PMID 25237811, 2014). "Ablation ofCyp8b1 (Cyp8b1−/−) prevents atherosclerosis inApoe−/− mice.Cyp8b1−/− mice have improved glucose homeostasis by increased GLP-1 secretion." (PMID 29188025, 2017). "The expression of other key atherosclerosis-related enzymes, including cytochrome P450 8B1 (CYP8B1) and lanosterol synthase (LSS), was downregulated, whereas the expression of cyclooxygenase 2 (COX-2) and aldo–keto reductase family 1 member C3 (AKR1C3) was induced by PFOS and PFOA." (PMID 40728694, 2025).
dyslipidemia (6 papers, 2014 to 2025). "Western blot analysis showed that NR5A2, CYP7A1, and CYP8B1 were lowly expressed in metabolic syndrome, and their expression levels were up-regulated after exercise (P < 0.05)." (PMID 37053002, 2023). "CYP8B1 catalyzes the synthesis of CA and plays a central role in intestinal cholesterol absorption and cholesterol gallstones, dyslipidemia, and the pathogenesis of diabetes." (PMID 31737069, 2019). "Additionally, several metabolic syndrome phenotypes were alleviated by Cyp8b1 deletion." (PMID 40499905, 2025). "After carrying out NR5A2 knockout or overexpression experiments, it was found that NR5A2 reduced the level of inflammation through CYP7A1/CYP8B1, and C/EBPβ-FASN-SCD1 reduced the level of apoptosis, thereby improving the metabolic syndrome." (PMID 37053002, 2023).
cholestasis (5 papers, 2018 to 2023). Impairment of the bile flow caused by obstruction within the liver, or outside the liver in the bile duct system. "CYP7A1, which serves as the rate-limiting enzyme in the classical BA synthesis pathway, and CYP8B1 were markedly downregulated in BDL-induced cholestasis." (PMID 32296329, 2020). "As expected, induction of cholestasis by LCA feeding resulted in a significant downregulation of Cyp7a1 and Cyp8b1, the rate limiting enzymes of bile acid synthesis." (PMID 31752395, 2019). "In accordance with the decrease in FGF19 in patients with cholestasis, BA-synthesized enzymes, including CYP7A1, CYP8B1, and CYP27A1, increased significantly in the liver." (PMID 30504803, 2018).
diabetes (5 papers, 2014 to 2022). "In HFD/STZ-induced diabetes mice model, mRNA level of Cyp8b1 was induced." (PMID 32489392, 2020). "To determine whether reduced CYP8B1 activity improves insulin sensitivity, we sequenced CYP8B1 in individuals without diabetes and identified carriers of complete loss-of-function (CLOF) mutations utilizing functional assays." (PMID 36107630, 2022).
hepatocellular carcinoma (5 papers, 2015 to 2025). A malignant tumor that arises from hepatocytes. "CYP8B1 is identified as a prognostic gene for survival analysis in hepatocellular carcinoma." (PMID 35874705, 2022). "On the other hand, we found suppressed expression of CYP8B1 and LSS after treatment with PFOS and PFOA, confirming a recent study with hepatocytes derived from a hepatocellular carcinoma." (PMID 40728694, 2025). "By using a cutoff value of β > 0.5, we identified five DME genes (CYP1B1, CYP8B1, GSTM2, GSTP1, and UGT3A2) that were regulated by DNA methylation in hepatoma cells." (PMID 26421064, 2015). "Among these DME genes, the downregulation of CYP1B1, CYP8B1, GSTM2, GSTP1, UGT2B15, and UGT3A2 in hepatoma cells could be explained by DNA methylation status." (PMID 26421064, 2015).
gallstones (4 papers, 2015 to 2023). Solid crystalline precipitates in the biliary tract, usually formed in the gallbladder, resulting in the condition of cholelithiasis. "Moreover, the induced CYP8B1 expression may correlate with the development of gallstones in human obstructive cholestasis due to gallstone blockage of bile ducts because gallstone formation has been shown to be averted with depletion of CA in mice." (PMID 25798860, 2015).
liver fibrosis (4 papers, 2018 to 2025). "Elevated Cyp8b1 expression may disrupt bile acid homeostasis, leading to hepatocyte injury and chronic inflammation, both of which are significant drivers of liver fibrosis." (PMID 41282184, 2025). "Consistent with the gene expression trend, higher CYP7A1 and lower CYP8B1, FXR, and SHP protein levels were observed in the liver fibrosis groups." (PMID 35637968, 2022).
colitis (3 papers, 2021 to 2024). Inflammation of the colon. "Instead, a recent study has alfo found that CA could increase inflammation in the gut and potentiate intestinal epithelial injury in colitis mice through hepatic CYP8B1-CA axis." (PMID 38983627, 2024). "On the other hand, suppression of hepatic Cytochrome P450 8B1 (CYP8B1), an enzyme synthesising cholic acid, restores ISC renewal and alleviates colitis in mice." (PMID 38386338, 2024).
type 2 diabetes (3 papers, 2018 to 2022). "In this study, we proved that metformin inhibits the expression of CYP8B1, thereby inhibiting the synthesis of CA, as a novo target for the treatment of type 2 diabetes." (PMID 31737069, 2019). "Metformin inhibits the expression of the enzyme (CYP8B1) required for the synthesis of 12α-hydroxylated bile acid and inhibits the synthesis of cholic acid, which may be effective targets for the treatment of type 2 diabetes." (PMID 31737069, 2019). "CYP8B1 mutation carriers showed decreased total cholesterol/HDL-C and APOB/APOA-I ratios, suggesting that CYP8B1 inhibition may reduce type 2 diabetes without proatherogenic lipid changes." (PMID 36107630, 2022).
Cirrhosis (2 papers, 2018 to 2024). A chronic disorder of the liver in which liver tissue becomes scarred and is partially replaced by regenerative nodules and fibrotic tissue resulting in loss of liver function. "This is consistent with the reduction in microsomal sterol 12α-hydroxylase (CYP8B1) levels that have previously been observed in the setting of PSC cirrhosis." (PMID 30332763, 2018).
colorectal cancer (2 papers, 2016 to 2022). A primary or metastatic malignant neoplasm that affects the colon or rectum. "This study has profiled the expression of the cholesterol metabolising enzymes CYP2R1, CYP7B1, CYP8B1, CYP27A1, CYP39A1, CYP46A1 and CYP51A1 in primary colorectal cancer tissue using a well-characterised cohorts of colorectal cancers." (PMID 27341022, 2016). "The findings of increased expression of CYP8B1 and CYP46A1 in primary colorectal cancer are novel findings." (PMID 27341022, 2016). "The intensity of immunostaining was significantly higher in primary colorectal cancer compared with normal colonic mucosa for CYP2R1 (p<0.001), CYP7B1 (p<0.001), CYP8B1 (p<0.001), CYP46A1 (p<0.001) and CYP51A1 (p=0.001)." (PMID 27341022, 2016). "Immunohistochemistry was performed on a colorectal cancer tissue microarray containing 650 primary colorectal cancers using monoclonal antibodies to CYP2R1, CYP7B1, CYP8B1, CYP27A1, CYP39A1, CYP46A1 and CYP51A1, which we have developed." (PMID 27341022, 2016). "CYP2R1, CYP7B1, CYP8B1, CYP46A1 and CYP51A1 all showed significantly increased expression in primary colorectal cancer compared to normal colonic mucosa with CY7B1 demonstrating the highest proportion of strong immunoreactivity in colorectal cancer compared to all other enzymes studied." (PMID 27341022, 2016). "However, CYP2R1 (p=0.034), CYP8B1 (p=0.002), CYP39A1 (p<0.001), CYP46A1 (p<0.001) and CYP51A1 (p=0.001) each demonstrated significantly reduced expression in paired lymph node metastasis compared to Dukes C (stage 3) colorectal cancer." (PMID 27341022, 2016).
hyperlipidemia (2 papers, 2020 to 2023). "The results of the current study are consistent with reports indicating that hepatic CYP7A1 and CYP8B1 expression are lowered in diet-induced hyperlipidemia models and that FGF15/19 suppressed expression of both these genes." (PMID 33036208, 2020).
inflammatory bowel disease (2 papers, 2023 to 2025). A spectrum of small and large bowel inflammatory diseases of unknown etiology. "Perturbations in bile acid metabolism are observed in patients with inflammatory bowel disease, where the overexpression of bile acids and the metabolic enzyme CYP8B1 can exacerbate intestinal barrier damage and impair repair functions." (PMID 40630428, 2025).
intrahepatic cholestasis (2 papers, 2023). A cholestasis characterized by impairment of the bile flow caused by obstruction located in the liver. "Polymorphic variants of CYLD, GC, MBL2, and ZNF572 genes have been collectively associated with the risk of preterm birth or recurrent late pregnancy loss, while dysregulated expression of CYP8B1 may be responsible for pregnancy intrahepatic cholestasis in mice." (PMID 36768581, 2023).
liver disease (2 papers, 2021). "Therefore, the downregulation of Cyp8b1 in the ACLI model might trigger harmful consequences during liver disease progression, further increasing the known risk of HCC in Abcb4−/− mice." (PMID 34360670, 2021). "Some studies demonstrated that CYP8B1 transcription was regulated by bile acids, which participated in lipid metabolisms and other liver diseases." (PMID 34257549, 2021).